CASC20 (cancer susceptibility 20)
Gene: Long non-coding RNA gene on chromosome 20 (6,446,723 to 6,580,186, forward strand). Ensembl gene ENSG00000229876.
Diseases named in the same sentence as CASC20 in open-access papers:
CASC20 is named in the same sentence as 8 diseases in open-access papers, as found by Europe PMC text mining. Sharing a sentence is not in itself a finding about the gene and the disease. The quoted sentences say what the papers report.
gastric cancer (1 paper, 2022). A primary or metastatic malignant neoplasm involving the stomach. "lncRNA cancer susceptibility 20 (CASC20) was reported to serve as a tumor promoter by promoting the metastasis of human gastric cancer cells by the miR-143-5p/MEMO1 molecular axis." (PMID 36105083, 2022).
osteoporosis (1 paper, 2024). A condition of reduced bone mass, with decreased cortical thickness and a decrease in the number and size of the trabeculae of cancellous bone (but normal chemical composition), resulting in increased fracture incidence. "CASC20 is a regulator of body height, BMI-adjusted waist circumference, and heel-bone mineral density (a measure of osteoporosis)." (PMID 38918595, 2024).
cancer (2 papers, 2020 to 2024). A tumor composed of atypical neoplastic, often pleomorphic cells that invade other tissues. "We found a significant locus adjacent to sodium voltage-gated channel alpha subunit 10 (SCN10A), and a borderline significant locus adjacent to cancer susceptibility 20 (CASC20)." (PMID 38918595, 2024). "Oncogenic lncRNAs in human cancer, including HOTAIR, MALAT1, PCA3, CASC15, and CASC20 are also annotated in dogs." (PMID 33194754, 2020).
lip (1 paper, 2025). "Novel loci include those mapping to LHX8 and TSBP1 (combined clefts), ARHGEF18 and ARHGEF19 (cleft lip with/without palate), FBN2 (cleft lip only), SLC35B3 (cleft palate only), CASC20 (Pierre Robin Sequence) and CHRM2 (non-syndromic cleft palate only)." (PMID 41075272, 2025).
CASC20 also shares sentences with these, for which no sentence is quoted: cleft lip (1 paper); cleft palate (1); orofacial cleft (1); tumor (1).